ERBB4 (erb-b2 receptor tyrosine kinase 4)
Diseases named in the same sentence as ERBB4 in open-access papers (continued):
Sharing a sentence is not in itself a finding about the gene and the disease.
Anxiety (20 papers, 2014 to 2025). Intense feelings of nervousness, tension, or panic often arise in response to interpersonal stresses. "ERBB4 modulates fear and anxiety through regulation of GABAergic interneurons within the amygdala and prefrontal cortex, with aberrations linked to PTSD-like phenotypes." (PMID 41462983, 2025). "The findings showed that removing ErbB4 from SST+ neurons led to increased anxiety and generalized fear, like PTSD symptoms, with specific alteration of neuronal activity." (PMID 39623093, 2024). "Genetic alteration of ventral hippocampus ErbB4 led to an elimination of nicotine withdrawal-related anxiety-like behaviors." (PMID 39258169, 2024). "It was previously shown that ErbB4 deletion in CeLSST neurons is sufficient to elevate anxiety levels." (PMID 39623093, 2024). "We also adopted the CRISPR/Cas9 system for region-specific KO of ErbB4, which revealed that ErbB4 deletion in SST+ neurons of the lateral division of the amygdala (CeL) caused elevated anxiety and PTSD-like fear generalization." (PMID 39623093, 2024). "Gomafu can bind to multiple splicing factors and participate in the alternative splicing of DISC1 and ERBB4.Gomafu knockout mice exhibit mild hyperactivity and anxiety-like behavior." (PMID 36226104, 2022). "ERBB4 is a major gene involved in fear responses, and the GABRB2 gene is reportedly associated with behavioral responses to anxiety in chickens and mice." (PMID 34072132, 2021). "In comparison, our mutant mice with ErbB4 deletion in LC-NE neurons presented significant hyperactivity and reduced anxiety." (PMID 30179154, 2018). "Additionally, SNPs in NRG3 have been linked to nicotine addiction and smoking cessation success in humans, translated from mice studies showing ErbB4 to play a role in anxiety-like behaviors during nicotine withdrawal." (PMID 39258169, 2024). "Remarkably, alterations in the ErbB4 expression in the amygdala and white matter could induce anxiety-like behaviors in mice." (PMID 36175956, 2022). "Likewise, the expression of Erbb4 is increased in CCK-SAP rats compared with control rats: mice with high anxiety phenotype display low levels of ErbB4 in the amygdala, and administration of its ligand neuregulin 1 is anxiolytic while enhancing GABAergic neurotransmission." (PMID 35965105, 2022). "In addition, decreased hypothalamic ErbB4 expression might mediate the increased HPA axis activity and anxiety in ERβ-deficient mice compared to WT mice during visceral stress from the gut." (PMID 36175956, 2022). "Overall, ErbB4 expression in SST neurons, specifically in the CeL, is most likely necessary for the proper regulation of anxiety levels and learned fear." (PMID 39623093, 2024). "Finally, we revealed that developmental deficiency of ErbB4 in serotonergic circuits impairs cognitive function related to specific types of memory in adult mice without affecting other emotional behaviors such as anxiety or coping behavior." (PMID 34957103, 2021). "ErbB4 deletion in dopaminergic neurons in the midbrain led to deficits in spatial/working memory but had no influence on locomotion or anxiety." (PMID 30179154, 2018). "Given the decreased ErbB4 expression in the hypothalamus of ERβ−/− mice in response to DSS, as well as its established role in regulating brain functions, we hypothesized that ErbB4 may be an important regulator of anxiety-like behavior in ERβ−/− mice with colitis." (PMID 36175956, 2022). "The only difference is that ErbB4 KO mice but not PV interneuron-specific ErbB4 KO mice exhibit reduced anxiety-like behaviors and deficits in cued and contextual fear conditioning, which might be caused by developmental disorders in ErbB4-deficient interneurons." (PMID 25805966, 2015).
Cognitive impairment (19 papers, 2014 to 2026). Abnormal cognition is characterized by deficits in thinking, reasoning, or remembering. "In view of the opposite changes of NRG1/ErbB4 and EGF/ErbB1, the expression of hippocampal NRG1/ErbB4 seems to be more directly linked with cognitive deficits in CCH." (PMID 29875654, 2018). "Besides, previous studies suggested that disturbance of Neuregulin1 (NRG1)/ErbB4 signaling is associated with cognitive impairments, as well as neuronal apoptosis and neuroinflammation in CNS." (PMID 29875654, 2018). "Blocking hippocampal NRG1/ErbB4 signaling or ablating ErbB4 attenuated synaptic and cognitive deficits." (PMID 38388921, 2024). "More specifically, mutations in NRG1/ERBB4 lead to impairments in AMPA and NMDA receptors’ spines structure and plasticity, and it has been attributed to cognitive deficits observed in SCZ patients." (PMID 34946848, 2021). "Pharmacological inactivation of HER4 has been shown to hasten the progression of epileptogenesis in rodent models, and heterozygous ERBB4 null mice are shown to have cognitive deficits and delayed motor development." (PMID 33603162, 2021). "Our findings reveal an intimate reciprocal relationship between ErbB4 and NMDA receptors with possible implications for the modulation of cortical microcircuits associated with cognitive deficits in psychiatric disorders." (PMID 26027736, 2015). "Evidence revealing the link between Nrg1/ErbB4 and cognitive deficits in patients with schizophrenia has begun to accumulate." (PMID 24782733, 2014). "Accumulating evidence has suggested that tight coupling of the ErbB4–PSD-95–NMDA receptor complex may underlie the pathophysiological molecular signature of psychiatric and cognitive disorders." (PMID 26637193, 2015). "Accumulating evidence suggest that de-coupling ErbB4–PSD-95–NMDA receptor interaction due to mutation or/and reduced expression of any of the member component may represent a key molecular signature of psychiatric episodes, cognitive disorders and altered long-term potentiation (LTP)." (PMID 26637193, 2015). "Additionally, several pathways including the ERBB4 signaling pathway (adjusted p = 2.82 × 10-3), driven by ERBB4, NRG1, and NRG3 may contribute to cognitive impairments." (PMID 42193047, 2026).
epilepsy (19 papers, 2013 to 2025). A brain disorder characterized by episodes of abnormally increased neuronal discharge resulting in transient episodes of sensory or motor neurological dysfunction, or psychic dysfunction. "Separate studies have also shown that exonic deletion of ERBB4 is associated with intellectual disability or epilepsy." (PMID 35073995, 2022). "Previous study showed that ErbB4 deletion in PV-positive neurons increased susceptibility to epilepsy." (PMID 28273943, 2017). "In summary, we demonstrate that 2q34 deletions that result in loss of exons of ERBB4 may cause autosomal dominant mild to moderate developmental delay, ID or epilepsy." (PMID 33603162, 2021). "Both NRG1 and ErbB4 have been implicated in epilepsy in mouse models and in humans, but a precise role and mechanism for NRG1/ErbB4 in human symptomatic epilepsy, a type of epilepsy with specific etiology and organic brain disease, remain unclear." (PMID 28273943, 2017). "Interestingly, alteration of Nrg1/ErbB4 signaling is implicated in epilepsy animal models and human patients, and disruption of Nrg1/ErbB4 signaling pharmacologically and/or genetically promotes kindling progression, which results in increased spontaneous seizures in kindling epilepsy model." (PMID 33536056, 2021). "NRG-1/ErbB4 signaling-dependent neuroprotection is vital for host survival in instances of CNS damage such as ischemic stroke, spinal cord injury, epilepsy, and experimental cerebral malaria infection." (PMID 39095837, 2024). "Overall, this case series further supports that haploinsufficiency of ERBB4 leads to non-syndromic intellectual disability or epilepsy." (PMID 33603162, 2021). "Nevertheless, our study demonstrates an important role of Nrg1/ErbB4 signaling in mediating the anti-seizure effects of KD and provide insight into the epilepsy treatment." (PMID 33536056, 2021). "Dysfunction of this NRG1/ErbB4 signaling in GABAergic neurons has been reported to induce epilepsy and psychiatric disorders in human where single nucleotide polymorphisms of these proteins were closely linked to E/I imbalance." (PMID 31780806, 2019). "In this study, using symptomatic epilepsy tissues from CA patients, we showed that the ErbB4 was significantly increased in the brains of CA patients with symptomatic epilepsy." (PMID 28273943, 2017). "Our previous study showed that ErbB4 expression was significantly decreased in the epilepsy tissues of mesial temporal epilepsy patients." (PMID 28273943, 2017). "To summarize, we found that the protein levels of NRG1 and ErbB4 were significantly increased, whereas Glu2B and Src phosphorylation were decreased in symptomatic epilepsy." (PMID 28273943, 2017). "In comparison, the symptomatic epilepsy tissues from the temporal lobe of CA patients presented increased ErbB4 protein levels." (PMID 28273943, 2017). "However, the exact roles and mechanism for NRG1/ErbB4 in human symptomatic epilepsy are still unclear." (PMID 28273943, 2017). "However, in symptomatic epilepsy patients, the ErbB4 signal was notably increased in the temporal lobe." (PMID 28273943, 2017). "The discrepancy between ErbB4 expression in mesial temporal epilepsy and symptomatic epilepsy suggests that ErbB4 may play different roles in the two types of epilepsy." (PMID 28273943, 2017). "Previous studies have shown that the neuregulin 1 (NRG1)-ErbB4 signaling pathway may regulate the excitability of fast-spiking neurons in the frontal cortex and participate in primary epilepsy pathogenesis." (PMID 28273943, 2017). "Given the sizable mutation frequency difference of ERBB4 between the epilepsy and non-neurologic cohorts, identification of the gene would have likely been possible using frequency information alone." (PMID 24086149, 2013).
epilepsy (continued). "The negative correlation between NRG1-ErbB4 and the phosphorylation of GluN2B, the increased NRG1/ErbB4 and decreased phosphorylation of GluN2B at Y1472, suggests that the NRG1-ErbB4 pathway may be protective against NMDAR-mediated hyperexcitability in symptomatic epilepsy." (PMID 28273943, 2017). "Two of these genes—ERBB4 and MHD2-are directly involved in epilepsy and have increased expression in GCD2/GCD3." (PMID 33986407, 2021). "Using fresh human symptomatic epilepsy tissues, we found that the protein levels of NRG1 and ErbB4 were significantly increased in the temporal cortex." (PMID 28273943, 2017). "The protein levels of ErbB4 and NRG1 were both drastically increased in the symptomatic epilepsy group." (PMID 28273943, 2017). "The difference among the three groups implies that epilepsy, but not CA, is responsible for the ErbB4 increase in CA patients with symptomatic epilepsy." (PMID 28273943, 2017). "We found that patients with symptomatic epilepsy showed a remarkable increase in protein levels of NRG1 and ErbB4 in the temporal cortex and a substantial decrease in the phosphorylation levels of Glu2B-pY1472 and Src-pY416, two downstream targets of NRG1-ErbB4 signaling." (PMID 28273943, 2017). "However, brain ErbB4 levels were similar between CA patients without symptomatic epilepsy and control groups." (PMID 28273943, 2017).
breast tumor (17 papers, 2006 to 2026). "Interestingly, ErbB4 is for instance associated with the acquired resistance to ErbB2-inhibitors in HER2+ breast tumors, probably via a shift in the dependency towards ErbB4 signaling following continuous ErbB2 blocking, though additional resistance mechanisms should account." (PMID 33912195, 2021). "The mRNA levels of ERalpha, ERbeta, epidermal growth factor receptor, ErbB2, ErbB3, ErbB4, ERRα, ERRβ, and ERRγ were determined in unselected primary breast tumors and normal mammary epithelial cells enriched from reduction mammoplasties." (PMID 28945747, 2017). "In agreement with these published results, here we show that, relative to control constructs, the ErbB4 Q646C mutant inhibits clonogenic proliferation of (or displays tumor suppressor activity in) MCF7 human breast tumor cells and of MCF10A human breast epithelial cells." (PMID 24791013, 2013). "In BRCA, the leading Canonical pathway hits are Constitutive Signaling by Aberrant PI3K in Cancer, PI3K AKT Signaling in Cancer, and multiple ERBB4-driven routes, reflecting the centrality of PI3K/AKT and ERBB networks in hormone receptor–positive breast tumors." (PMID 41363728, 2026).
glioblastoma (17 papers, 2014 to 2025). The most malignant astrocytic tumor (WHO grade IV). "Overexpression of ErbB4 has been identified in medulloblastomas, pilocytic astrocytomas, ependymomas, and glioblastomas (GBMs)." (PMID 36119496, 2022). "This alanine residue is perfectly conserved within the Furin-like domain among other epidermal growth factor genes and appears mutated also in ERBB2 and ERBB4, although not in glioblastoma." (PMID 26860319, 2016). "We found that EGFR and ERBB2 mRNA expression levels were higher in glioblastoma (GBM, WHO IV) than in other grades (WHO grade II & III), while the ERBB3 and ERBB4 mRNA expression levels were the opposite." (PMID 33892666, 2021). "High PTPRZ-B levels, as in glioblastoma cells, thus may lead to decreased ErbB4 activity in two ways; by sequestering PSD95 and preventing PDZ-mediated ErbB4 homodimer formation as well as by directly dephosphorylating ErbB4." (PMID 29439552, 2018).
non-small cell lung carcinoma (17 papers, 2008 to 2026). A group of at least three distinct histological types of lung cancer, including non-small cell squamous cell carcinoma, adenocarcinoma, and large cell carcinoma. "Other evidence of miR-193a association with PI3K/Akt has been shown in non-small-cell lung cancer, where it suppresses metastasis by targeting the receptor tyrosine-protein kinase ERBB4, a member of the epidermal growth factor (EGF) receptor subfamily, and inhibiting the downstream PI3K/Akt cascade." (PMID 40801567, 2025). "Afatinib is an oral epidermal growth factor receptor tyrosine kinase inhibitor targeting the ERBB family (including EGFR, HER2, ERBB3, and ERBB4), and has been approved for the treatment of locally advanced or metastatic non-small-cell lung cancer (NSCLC) with an EGFR-sensitive mutation." (PMID 39406703, 2024). "ERBB3/ERBB4 heterodimers may also be active and relevant for disease relapse in non-small cell lung cancer, where inhibition of ligand-dependent ERBB3/ERBB4 signaling with a NRG1-blocking antibody enhanced the magnitude and duration of response to chemotherapy in various mouse models." (PMID 26745281, 2016). "Moreover, mutations observed in ErbB4 in non-small cell lung cancer patients experimentally lead to changes in ErbB2-ErbB4 heterodimer signaling promoting cell proliferation but not differentiation, and to increased phosphorylation likely because of stabilization of the ErbB4 active dimer state." (PMID 31536605, 2019). "It has been reported that ERBB4 and S6K2 are the direct targets of miR-193a-3p and that PIK3R3 and mTOR are the direct targets of miR-193a-5p in non-small-cell lung cancer." (PMID 28611587, 2017).
prostate carcinoma (17 papers, 2005 to 2025). A carcinoma that arises from epithelial cells of the prostate gland. "The total expression of the other ErbB family member, HER4 (ErbB4), was low or undetectable in most prostate cancer cell lines assessed." (PMID 40857406, 2025). "The EGFR/ERBB4, MET and IGF-1R families of growth factor receptor have been implicated in prostate cancer." (PMID 35954439, 2022). "The monoclonal antibody ERBB4 therapy is effective in breast, lung, and prostate cancer cells in vitro and in vivo." (PMID 33503190, 2021). "ErbB-related pathways were identified in the metastatic network, including the ErbB network pathway, ErbB4 pathway, Her2 pathway, ErbB2/ErbB3 signaling pathway and the EGFR pathway, which are implicated in prostate cancer progression and metastasis." (PMID 23782521, 2013). "Long non-coding RNA Erbb4-IR is downregulated in prostate cancer and can predict the prognosis." (PMID 33869042, 2021). "This family of proteins has been extensively studied in breast, lung, colon and prostate cancer and its members include EGFR/ErbB1, Her-2/ErbB2, Her-3/ErbB3 and Her-4/ErbB4." (PMID 24281100, 2010). "Studies have suggested a role for EGFR and ERBB3 in the development of prostate cancer (PC), while the involvement of ERBB2 and ERBB4 remains unclear." (PMID 33918389, 2021).